SHC1 (SHC adaptor protein 1)
Diseases named in the same sentence as SHC1 in open-access papers (continued):
Sharing a sentence is not in itself a finding about the gene and the disease.
lung carcinoma (continued). "Aiolos promotes anchorage independence in lung cancer by downregulating several adhesion-related genes, and also by blocking anoikis through the silencing of the anchorage reporter gene p66Shc, an isoform of the SHC1 gene." (PMID 31696060, 2019). "The trend of EMT-related markers showed that SHC1 silencing could inhibit EMT in lung cancer cells." (PMID 35706930, 2022). "However, the role of SHC1 in lung cancer needs further study." (PMID 35706930, 2022). "Therefore, the SHC1 gene in lung cancer has been studied in depth." (PMID 35706930, 2022). "Therefore, targeted interference with SHC1/EGFR interactions may be a new strategy for the lung cancer treatment." (PMID 35706930, 2022). "Furthermore, high expression of SHC1 was also associated with worse OS in stages 1 and 2 but not stage 3 lung cancer patients (OS HR = 1.86, logrank P < 0.01; OS HR = 1.7, logrank P = 0.0041; OS HR = 0.94, logrank P = 0.8145)." (PMID 34117717, 2021). "Furthermore, survival analysis for SHC1 expression and methylation indicated that SHC1 could serve as a prognostic biomarker in lung cancer patients." (PMID 34117717, 2021). "Moreover, higher expression of SHC1 was also associated with worse OS in patients with stages 1 and 2 but not stage 3 lung cancer." (PMID 34117717, 2021). "In addition, high SHC1 expression lung cancer patients had poorer OS in AJCC stage M0." (PMID 34117717, 2021). "However, very little is known about the role of SHC1 in lung cancer." (PMID 34117717, 2021). "In addition, although some EDN1(endothelin-1)-related BTS pairs and SHC1(Src homology 2 domain containing transforming protein)-related BTS pairs are shared in lung cancer tissue in current and former smokers, a considerable number of differing patterns are evident." (PMID 20628618, 2010). "Immunohistochemical staining was utilized for identifying the expression of LDHA, CDKN3, SHC1, and BTK in 127 lung cancer samples." (PMID 40182622, 2025). "The complex of SHC1 and EGFR was the potential therapeutic target to restrain lung cancer metastasis." (PMID 38602568, 2024). "Concluding our investigation, qRT-PCR experiments confirmed the heightened expression levels of EPHX1, LDHA, SHC1, MYO6, and TLE1 in lung cancer cell lines." (PMID 37965333, 2023). "The results showed that SHC1 or EGFR overexpressed in A549 and NCI–H446 lung cancer cells significantly increased proliferation and invasion capacity compared with the control group." (PMID 35706930, 2022). "The SHC1, FKBP4, NRAS, and KRAS had higher expressions in lung cancer tissues compared with lung normal tissues in LUAD." (PMID 33936178, 2021). "We identified ARHG5 from the lung cancer cell line TAP data as prey proteins of GRB2 and SHC1 baits." (PMID 24189400, 2013). "Mutant EGFR pulldowns identified MAPK adaptors GRB2 and SHC1 as well as ERRFI and UBS3B tyrosine phosphatase, all consistent with our results described in the lung cancer cell lines harboring mutant EGFR." (PMID 24189400, 2013). "GRB2, SHC1, ERRFI, and UBS3B were found both in EGFR-mutant lung cancer cell lines and in AALE cells with mutant EGFR as a bait and thus represented logical choices to further examine as secondary baits." (PMID 24189400, 2013). "Additionally, proteins such as SHC1, MUC1, and ADAM15 display high betweenness centrality scores, indicating their importance as mediators in lung cancer progression." (PMID 40165937, 2025). "SHC1 interacts with EGFR to form a protein complex, which may be a new target for lung cancer metastasis." (PMID 35706930, 2022). "Meanwhile, the effect of SHC1 and EGFR on lung cancer was analyzed." (PMID 35706930, 2022). "In conclusion, SHC1 and EGFR are expected to become new therapeutic targets for lung cancer." (PMID 35706930, 2022). "Overexpression of SHC1 was correlated with poorer OS in female lung cancer patients as well as the patients with stages 1 and 2 but not stage 3 lung cancer." (PMID 34117717, 2021).
lung carcinoma (continued). "SHC1 expression level may influence the OS in LUAD patients and the gender, stage, and metastasis stage were also the significant prognostic factors in lung cancer patients." (PMID 34117717, 2021). "Therefore, high‐expressed SHC1 may influence OS in LUAD patients and the gender, stage and metastasis stage were also the significant prognostic factors in lung cancer patients." (PMID 34117717, 2021).
gastric cancer (9 papers, 2021 to 2026). A primary or metastatic malignant neoplasm involving the stomach. "Hyper activating Shc1–SHCBP1–PLK1–MISP axis impairs sensitivity of HER2-positive gastric cancer to trastuzumab." (PMID 37280713, 2023). "In this study, the authors demonstrate that HER2 promotes tumorigenesis in gastric cancer by regulating mitotic progression through a Shc1-SHCBP1-PLK1-MISP axis and they identify a compound, TFBG, able to disrupt SHCBP1/PLK1 interaction and to synergize with trastuzumab." (PMID 33990570, 2021). "Similarly, MST1R had interactions with AKT, AKT1, and MST1, while LTR interacted with IRS1, CBL, PIK3C and SHC1, none of which have been found to be associated with gastric cancer before." (PMID 37287033, 2023). "We found that TFBG partly suppressed EGF-induced Shc1 and SHCBP1 dissociation, which suggested that the feedback inhibition on Shc1–SHCBP1 of TFBG is one of the reasons why TFBG sensitize gastric cancer to trastuzumab." (PMID 33990570, 2021). "Similarly, in gastric cancer, HER2 fuels tumor growth by regulating cell mitotic progression through the Shc1-SHCBP1-PLK1-MISP pathway." (PMID 39668816, 2024). "VWF, SHC1, and CAP2 have been reported to be elevated in LNM-positive patients with gastric cancer." (PMID 37158593, 2023).
pancreatic cancer (8 papers, 2014 to 2021). "Loss of SHC1 was answerable for the development of pancreatic cancer, but inactivation of this gene may be involved in the pathogenesis of GBM." (PMID 31137733, 2019). "In addition, knockdown by siRNA of adaptor protein SHC1 in pancreatic cancer cells reduces gemcitabine efficacy." (PMID 29023490, 2017). "However, in pancreatic cancer, miR-365 promote the resistance to Gemcitabine, a standard chemotherapeutic agent for pancreatic cancer, by directly targeted adaptor protein Src Homology 2 Domain Containing 1 (SHC1) and apoptosis-promoting protein BAX." (PMID 24949940, 2014). "Notably, both SHC1-engaged SRC and gp130-activated JAK2 signals increased the phosphorylation of STAT3 [Y705], a critical step in pancreatic cancer progression." (PMID 34921158, 2021). "The siRNA-based knockdown of SHC1 and BAX increased gemcitabine resistance, indicating the miR-365/SHC1/BAX axis might influence the survival of pancreatic cancer cells." (PMID 24899890, 2014).
bladder cancer (6 papers, 2020 to 2022). "A recent study also showed that upregulated SHC1 expression could act as a tumor promoter in bladder cancer and an underlying downstream of DEPDC1B." (PMID 35601500, 2022). "Furthermore, it was reported that SHC1 was associated with cancer development and progression through regulating cell proliferation, apoptosis and migration in bladder cancer." (PMID 34117717, 2021). "In a different study it was revealed that RAB14 has a carcinogenic effect in bladder cancer by downregulating SHC1 expression." (PMID 35601500, 2022). "To investigate the synergistic effect of DEPDC1B and SHC1 on bladder cancer, we constructed T24 cells that overexpressed DEPDC1B, and T24 cells that simultaneously overexpressed DEPDC1B but with the KD of SHC1." (PMID 33203836, 2020). "To further investigate the role of SHC1 in bladder cancer, we constructed a SHC1 KD cell model and verified thus using the method described for DEPDC1B KD DEPDC1B." (PMID 33203836, 2020). "All the results showed the role of SHC1 as a tumor promotor in bladder cancer and a potential downstream of DEPDC1B." (PMID 33203836, 2020). "In conclusion, we found the upregulated expression of DEPDC1B and SHC1 in tumor tissues of bladder cancer." (PMID 33203836, 2020). "The upregulation of SHC1 in bladder cancer tissues and its highly abundant expression in bladder cancer cell lines were also demonstrated by IHC and qPCR, respectively." (PMID 33203836, 2020). "Through RNA sequencing, the potential downstream of DEPDC1B in the regulation of bladder cancer was screened and SHC1 was identified as the most promising candidate." (PMID 33203836, 2020). "A previous study showed that SHC1 facilitated the development of bladder cancer." (PMID 35013128, 2022). "SHC1 is an essential molecule that DEPDC1B regulates the evolution of bladder cancer progression." (PMID 35903358, 2022). "SHC1 knockout can reduce the effect of DEPDC1B on bladder cancer induction." (PMID 35903358, 2022). "Therefore, the regulation of bladder cancer by DEPDC1B through SHC1 make it a potential therapeutic target for bladder cancer treatment." (PMID 33203836, 2020). "More importantly, SHC1 KD could attenuate DEPDC1B overexpression-induced promotion of bladder cancer." (PMID 33203836, 2020). "More importantly, the investigation of the synergistic effects of DEPDC1B and SHC1 on bladder cancer showed that SHC1 KD could alleviate or even reversed the regulation of bladder cancer by DEPDC1B overexpression." (PMID 33203836, 2020). "In summary, RNA sequencing indicated that DEPDC1B may regulate the development of bladder cancer by targeting SHC1." (PMID 33203836, 2020). "Herein, we found that SHC1 KD could significantly inhibit cell proliferation and colony formation of bladder cancer cells, while promoting cell apoptosis." (PMID 33203836, 2020). "Both DEPDC1B and SHC1 could act as tumor promotor in the development and progression of bladder cancer, through regulating cell proliferation, colony formation, cell apoptosis and cell migration." (PMID 33203836, 2020). "Therefore, the KD of SHC1 exhibited similar inhibitory effects on bladder cancer as DEPDC1B KD." (PMID 33203836, 2020). "Moreover, SHC1 KD also suppressed cell migration of bladder cancer cells." (PMID 33203836, 2020). "Moreover, a mechanistic study found that SHC1 may be an important route through which DEPDC1B regulates the development of bladder cancer." (PMID 33203836, 2020). "Moreover, the effects induced by KD of candidates including SHC1, VEGFC, VEGFR3, and ERK1/2 were evaluated by cell proliferation assay, displaying SHC1 as the strongest inhibitor of bladder cancer proliferation." (PMID 33203836, 2020).
lung adenocarcinoma (6 papers, 2016 to 2025). A carcinoma that arises from the lung and is characterized by the presence of malignant glandular epithelial cells. "The expression of SHC1 in lung adenocarcinoma tissues was significantly higher than that in paracancer tissues." (PMID 35706930, 2022). "In this study, we firstly found that SHC1 expression was up‐regulated both in lung adenocarcinoma (LUAD) and in lung squamous cell carcinoma (LUSC) tissues." (PMID 34117717, 2021). "The expression of LDHA, CDKN3, and SHC1 were significantly raised in lung adenocarcinoma compared to non-cancer cells, whereas BTK expression was higher in non-cancer than in cancer cells (Figures 8A2, B2, C2, D2)." (PMID 40182622, 2025). "Though, VEGFR2 shares with EGFR key intracellular partners such as SHC1, protein tyrosine kinase 2, and phospholipase C. EGFR-mutant lung adenocarcinoma patients who acquired EGFR-TKI treatment resistance may benefit from blocking VEGFR2 related angiogenesis and tumor growth." (PMID 31570733, 2019). "In a word, our research shows that the expressions of key genes of sphingolipid metabolism, such as LDHA, CDKN3, SHC1 and BTK, are obviously different from those of non-cancerous tissues in lung adenocarcinoma, and can obviously affect the prognosis of LUAD patients." (PMID 40182622, 2025).
atherosclerosis (5 papers, 2017 to 2024). A disease characterized by the build-up of fatty material and calcium deposition in the arterial wall resulting in partial or complete occlusion of the arterial lumen. "The direct inhibition of CDH5 following ETS1 inhibition led to the predicted activation of SHC1-induced atherosclerosis in this model." (PMID 39125657, 2024). "Therefore, by modulating LXR-driven ABCA1 gene expression through the SHC1/PI3K/AKT/PPARγ/LXRα axis, LRP1 is presenting itself as a pivotal regulator of the metabolic as well as inflammatory processes underlying atherosclerosis." (PMID 29144234, 2017).
colon cancer (5 papers, 2020 to 2023). "Overexpression of SHC1 is associated with poor survival in stage IIA colon cancer." (PMID 35686121, 2022). "Furthermore, overexpression of SHC1 is associated with low survival rates in stage IIA colon cancer." (PMID 35692836, 2022). "According to a 2007 study by Dihal, QC can lower the expression of Shc1 in rats with colon cancer." (PMID 38129872, 2023). "Also, overexpression of SHC1 was correlated with low survival in stage IIA colon cancer." (PMID 32028264, 2020).
glioma (5 papers, 2015 to 2024). A benign or malignant brain and spinal cord tumor that arises from glial cells (astrocytes, oligodendrocytes, ependymal cells). "The network topology analysis performed in this study revealed a set of central nodes associated to glioma malignancy, such as Map3k14, Mapk1, Actn4, Hspa5, Atf2, Rac1,E2f1, Shc1, Pik3ca, Akt1, Vim and Egr1." (PMID 26582089, 2015). "Consistently, the enhanced expression of SHC1 was associated with higher WHO grade of glioma." (PMID 38763954, 2024). "Genes associated with the neuronal differentiation pathway (Pcsk9, Runx1, Cebpb, Fzd4, Wnt7a, Ascl1, Fzd2, Edn3, Olig2, and Gpc2), gliomas (Shc1, Cdk4, E2f2, and Ccnd1), and cell cycle (Bub1b, Bub, Ccnb1, Ccnb2, and Cdc20) were significantly downregulated." (PMID 36147849, 2022).
breast tumors (4 papers, 2017 to 2020). "To assess differences in expression of all three SHC1 protein isoforms in human breast tumors, we have analyzed 9 independent breast cancer tumor samples (T) paired with matched normal protein samples (N) from tissues obtained from MCW Tissue Bank." (PMID 31202267, 2019). "Expression of the p66SHC transcript, the lesser-expressed Shc1 transcript, was below detectable levels in most normal and some breast tumor samples (data not shown)." (PMID 31202267, 2019).
colorectal cancer (4 papers, 2020 to 2025). A primary or metastatic malignant neoplasm that affects the colon or rectum. "Numerous studies have associated SHC1 with various malignancies, where its overexpression significantly impacts the prognosis of patients with hepatocellular carcinoma (HCC), colorectal cancer, and esophageal squamous cell carcinoma." (PMID 40953006, 2025). "Another study demonstrated that mir-5582-5p targets SHC1, inducing apoptosis and cell cycle arrest in colorectal cancer cells." (PMID 35601500, 2022). "In colorectal cancer, SHC1 was identified as a target of tumor suppressor miR-5582-5p to induce cell apoptosis and cell cycle arrest of colorectal cancer cells." (PMID 33203836, 2020). "Additionally, a recent study found that targeting SHC1 with mir-5582-5p induced cell apoptosis and cycle arrest in colorectal cancer." (PMID 35601500, 2022).
diabetes (4 papers, 2015 to 2025). "This study conducted an in-depth analysis of the GSE34451 dataset and identified 185 differentially expressed genes that form a complex regulatory network with SHC1 in the hippocampal tissues of a diabetes model." (PMID 40537751, 2025). "However, other genes such Vamp2, Chi3l3 and Shc1 were both significantly overexpressed in mice developing diabetes late and expression correlated with time of diabetes onset (correlation coefficients 0.841, 0.681 and 0.718; P-values 0.004, 0.035 and 0.024, respectively)." (PMID 26366287, 2015).
hepatocellular carcinoma (4 papers, 2020 to 2025). A malignant tumor that arises from hepatocytes. "Previous research demonstrated that high SHC1 expression predicts poor survival in hepatocellular carcinoma (HCC) patients." (PMID 35601500, 2022).
clear cell renal cell carcinoma (3 papers, 2021 to 2022). "Previous studies have suggested that SHC1 associated with imbalance in integrin expression may be a prognostic predictor of clear cell renal cell carcinoma (ccRCC)." (PMID 35692836, 2022).
Cognitive impairment (3 papers, 2020 to 2025). Abnormal cognition is characterized by deficits in thinking, reasoning, or remembering. "We, therefore, inferred that Shc1 might be a potential key therapeutic target against cognitive impairment after CA/CPR." (PMID 32693388, 2020).
ovarian carcinoma (3 papers, 2014 to 2025). A malignant neoplasm originating from the surface ovarian epithelium. "In sporadic ovarian cancers, SAM analysis identified up-regulation of e.g. SHC1, which is involved in protein tyrosine kinase activity, and FSCN1, which is related to protein binding (online resource 3)." (PMID 24848881, 2014).
type 2 diabetes (3 papers, 2013 to 2015). "Indeed, three members of this subnetwork (i.e. MAPK1, INSR, SOCS3) belong to the Type II diabetes mellitus pathway, which fall into the bigger insulin signaling pathway together with SHC1 and ELK1." (PMID 23885764, 2013).
depression (2 papers, 2017 to 2023). "Meanwhile, antidepressant drugs may exert beneficial effects on the insulin receptor phosphorylation pathway through the Shc1/Grb2 complex, which further supports the potential use of Sch1 for depression drug development." (PMID 37649561, 2023). "These protein targets, especially hubs, and the functional nodes, MTOR, CDK6, SHC1, RCOR1 CCNA2 and STAT3, have been already reported to be involved in depression." (PMID 28954415, 2017).
endometriosis (2 papers, 2008 to 2023). The growth of functional endometrial tissue in anatomic sites outside the uterine body. "Our data show that AXL and SHC1 are differentially expressed in endometriosis implicating the PI3K and MAPK pathways in this disease." (PMID 19055724, 2008). "The MAPK pathway is therefore constitutively activated in both human endometriosis and in the mouse endometriosis model, and the overexpression of SHC1 is an intriguing mechanism for the activation of this pathway in human endometriosis." (PMID 19055724, 2008). "A previous study showed that upregulation of the adaptor protein SHC1 had the ability to activate the PI3K-Akt and/or MAPK pathways in endometriosis samples." (PMID 36660246, 2023). "Because of their expression pattern, SHC1, ACTN4, and AXL, were identified as promising endometriosis-related candidate genes, and their expression patterns were further investigated at the protein level by immunohistochemistry." (PMID 19055724, 2008). "Next, we investigated the possibility that downstream pathways in which AXL and SHC1 are involved, PI3K/Akt and MAPK respectively, may be activated in endometriosis." (PMID 19055724, 2008). "As overexpression of AXL and SHC1 theoretically activates both PI3K-Akt and MAPK pathways, dysregulation of these genes in human endometriosis may correspond to oncogenic activation of K-ras or biallelic losses of Pten in the mouse model of the disease." (PMID 19055724, 2008). "In human endometriosis, the PI3K-Akt and MAPK signaling pathways may be activated via overexpression of AXL and SHC1, respectively." (PMID 19055724, 2008). "Furthermore, the proto-oncogenes AXL, SHC1, and JUND are elevated in endometriosis." (PMID 19055724, 2008).